CTLA4 (cytotoxic T-lymphocyte associated protein 4)
Diseases named in the same sentence as CTLA4 in open-access papers (continued):
Sharing a sentence is not in itself a finding about the gene and the disease.
lung cancer (continued). "Surprisingly, GARS not only correlated with the IPS score of PD-1 and CTLA4 but also correlated with the prognosis of lung cancer patients who received PD-1/PD-L1 therapy." (PMID 35127727, 2021). "Materials and methods: PubMed, Embase, Cochrane library and major conference proceedings were systematically searched for all randomized controlled trials (RCTs) in lung cancer using PD-1/PD-L1/CTLA-4 inhibitors." (PMID 32315071, 2020). "CTLA‐4 and PD‐1 inhibitors can be used to stimulate the T cells in COPD to mitigate the risk of disease progression and lung cancer, but the activation of cytotoxic T cells can influence the development of emphysema via the apoptosis of structural cells." (PMID 31829519, 2020). "Epigenetic studies in lung cancer have shown that promoter regions of the CTLA-4, PD-1, and PDL-1 genes can be hypomethylated, which in turn associates with upregulated expression of these genes in the tumor microenvironment." (PMID 32258034, 2020). "Immune control inhibitor drugs (anti-PD1/PD-L1/CTLA-4) (ICIs) are showing efficacy in the treatment of lung cancer." (PMID 33066479, 2020). "Patients with metastatic, KRAS-mutated lung cancer, treated with at least one cycle of a PD-1 inhibitor or an anti-PD-1/PDL-1 and anti-CTLA-4 combination regimen, had STK11/LKB1 mutations largely drive the primary resistance to PD-1 blockade, in any regimen." (PMID 32258034, 2020). "The phase 3 study CheckMate 227 was the first trial that showed positive results in dual checkpoint inhibition (anti-CTLA-4 and PD-1) in the field of lung cancer." (PMID 33014826, 2020). "The overexpression of CTLA-4 on Tregs is highly observed in lung cancer, indicating that CTLA-4 contributes to immune tolerance and immune evasion." (PMID 32847045, 2020). "Multiple studies investigated the efficacy of anti-PD-1/PD-L1 plus anti-CTLA-4 antibodies in lung cancer." (PMID 31196207, 2019). "Clinical data show that an increase in serum interferon-β is detectable after radiation and correlates with objective systemic response to radiation and CTLA-4 blockade in lung cancer patients." (PMID 31752991, 2019). "The aim of this study was to evaluate PD-1 and CTLA-4 expression on T cells in a different maturation status: from naïve cells to memory activated T cells in the lung cancer TME and systemic circulation." (PMID 31010080, 2019). "Recent studies evaluated the biodistribution of 64Cu-labeled ipilimumab using PET imaging, with a persistent high accumulation in CTLA-4-expressing lung cancer xenografts." (PMID 30506221, 2019). "Limitations of this analysis include the single-center setting, the preponderance of lung cancer cases, and the limited number of cases treated with anti–CTLA-4 therapies." (PMID 31532516, 2019). "Limitations of this study include the single-centre setting, the predominance of a single cancer type (lung cancer), the paucity of anti-CTLA4 cases and the inherent challenges of clinically diagnosing and characterising many irAEs." (PMID 30377338, 2019). "The use of “TIL signatures” as biomarkers to predict response to immune checkpoint inhibitors (i.e., anti-PD-1/PDL1, CTLA4) hold the potential to augment the efficacy of lung cancer therapy and, ultimately, increase lung cancer patients’ overall survival." (PMID 30658453, 2019). "A higher proportion of CTLA-4 was found in BALF from the lung with lung cancer when compared with the opposite “healthy” lung and peripheral blood." (PMID 31867335, 2019). "In recent years, several immunotherapies have been approved for the treatment of lung cancer, namely PD-1 checkpoint inhibitors nivolumab and pembrolizumab and the anti-CTLA-4 inhibitor ipilimumab." (PMID 31111237, 2019). "We previously demonstrated a significantly elevated proportion of CTLA-4+ Tregs in the lung cancer environment assessed by BALF analysis, when compared with the systemic compartment." (PMID 31010080, 2019).
lung cancer (continued). "Thus, modulating the immune response by targeting PD-1, PD-L1 or CTLA-4 in lung cancer might cause varying effects in the normal tissue, depending on the time point (acute versus chronic) of application, especially in a setting where ICI is given after radiotherapy of the thoracic region." (PMID 30577587, 2018). "We found significant differences of Tregs proportion and Tregs with (in) CTLA-4 expression between the local lung cancer environment and opposite lung and systemic response." (PMID 27866241, 2017). "As there were several types of cancer in the immunomodulation cohort, we also compared the PD-1 and CTLA-4 mRNA expression between the 7 lung cancer patients and 18 other malignancies." (PMID 28881603, 2017). "The increased proportion of Tregs, high expression of Foxp3 and CTLA-4 on tumor infiltrating and peripheral blood lymphocytes have been observed in lung cancer." (PMID 27866241, 2017). "We observed the difference in CTLA-4 cellular distribution in lung cancer: the ratio of surface to the intracellular expression of CTLA-4 was higher in TME when compared to peripheral blood." (PMID 28470464, 2017). "Little is known about the population of Tregs with two forms of CTLA-4: surface (s) and intracellular (in) in the lung cancer environment." (PMID 27866241, 2017). "The development of effective, immune checkpoint inhibitorssuch asPDL-1 (CD274), PD-1 and CTLA-4 has brought to the forefront the importance of the immune system in the treatment of lung cancer." (PMID 28105457, 2016). "The aim of our study was to evaluate the level of CTLA-4 mRNA expression in lung cancer tissue and to assess its relationship with two chosen CTLA-4 polymorphisms, affecting the leader sequence of CTLA-4 protein (+49A/G) and the promoter (−318C/T) of the gene." (PMID 23936819, 2013). "The aim of our work was to assess the level of CTLA-4 mRNA expression in lung cancer tissue, and we confirmed the increased gene expression in nearly 75% of NSCLC samples." (PMID 23936819, 2013). "In fact, our analysis of CTLA-4 expression revealed the significantly higher mRNA expression level in the lung cancer tissue samples carrying −318TT genotype." (PMID 23936819, 2013). "Recently, CTLA-4 protein expression has been reported to be significantly higher in primary lung cancer samples and precancerous lesions than in normal lung tissue." (PMID 23936819, 2013). "Conversely, synergy with etoposide and gemcitabine was also observed in the M109 lung carcinoma model in which CTLA-4 blockade was inactive, even when these chemotherapeutic agents demonstrated modest effect as monotherapy." (PMID 23873089, 2013). "The positive rate of CTLA-4 in primary lung cancer tissue and precancerous lesion was significantly higher than that in normal lung tissue (P < 0.05)." (PMID 20704820, 2010). "While immune checkpoint inhibitors (ICIs) targeting the PD-1 or CTLA-4 have achieved great success in the field of lung cancer in recent years, the efficacy of ICIs remains suboptimal, with only a fraction of patients responding positively and benefit from ICIs." (PMID 40855046, 2025). "Higher levels of CTLA-4 expression are often seen in more advanced stages of lung cancer." (PMID 39941799, 2025). "In the early stages of lung cancer, CTLA-4 expression may be lower because the immune system is still actively trying to fight the cancer cells." (PMID 39941799, 2025). "We found that combining MAP and anti‐CTLA4 antibodies could notably augment antitumor efficacy in patients with colorectal and lung cancers." (PMID 39499771, 2025). "Seeing as lung cancers are commonly treated with ipilimumab, a CTLA-4 inhibitor, it remains unclear whether cancer type or ICI regimen plays a larger role in increasing the risk of neuro-ophthalmic irAEs." (PMID 39595113, 2024).
lung cancer (continued). "Thus, this review highlights the role of dual blockade immunotherapy targeting PD-1/PD-L1 and CTLA-4 in treating lung cancer, and further elucidates its pre-clinical mechanisms and current advancements in clinical trials." (PMID 39068460, 2024). "Data from recent studies suggest that targeting CTLA-4 and Treg cells with immunotherapy may have an advantage in lung cancer patients." (PMID 38234663, 2024). "Also targeting the PD-1, programmed cell death ligand 1 (PD-L1), and CTLA4 pathways, demonstrate significant advances in lung cancer treatment." (PMID 38234663, 2024). "These patients predominantly presented with lung cancer and were treated with CTLA-4 blockade." (PMID 39595113, 2024). "Three years later, the biodistribution of [64Cu]Cu-DOTA-ipilimumab in mice bearing lung cancer CTLA-4-expressing tumor xenografts was evaluated, demonstrating how the tumor-tracer uptake in vivo could correlate with the CTLA-4 expression in tumor cells." (PMID 38067379, 2023). "Consistently, lung cancer patients who responded to RT and CTLA-4 blockade had larger TIL-TCRs." (PMID 37833255, 2023). "In addition, ARAC has shown efficacy in another model of lung cancer (KLN-205), which is unresponsive to combination treatment with cytotoxic T-lymphocyte associated protein 4 (CTLA4) and PD-1 antibodies." (PMID 38022518, 2023). "However, lung cancer is mostly treated with anti-PD(L)-1 and less frequently with anti-CTLA-4 monotherapy." (PMID 36811715, 2023). "Immune checkpoint inhibitors (ICIs) play a crucial role in the treatment of lung cancer and can be classified into two main groups: Anti-cytotoxic T lymphocyte antigen-4 (Anti-CTLA-4) and anti-T-cell receptor programmed cell death-1 or its ligand (Anti-PD-1 and Anti-PD-L1)." (PMID 37760516, 2023). "Blocking CTLA-4 and PD-1 pathways has proved efficacy in lung cancer." (PMID 37760516, 2023). "In addition, the new strategy of boosting tumor-killing immunity via PD-1/PD-L1 and CTLA4 has advanced the treatment of lung cancer." (PMID 35743687, 2022). "Moreover, new research shows that SETDB1 fuels the phenotype of lung cancer by modulating the epigenome and resists anti-CTLA4 and anti-PD1 combination therapy." (PMID 36092910, 2022). "The percentage of CD137+ regulatory T cells (Tregs) in the blood of lung cancer patients was also increased, and further enriched at the tumor site; Foxp3, CTLA-4, IL-10, IL-35-Ebi3, sCD137 and costimulatory molecules expression were also higher, indicating increased immunosuppressive activity." (PMID 35197968, 2022). "Moreover, increased CD274, PDCD1, and CTLA4 levels are strongly related to the overexpression of POSTN in lung cancer, especially LUSC." (PMID 35508298, 2022). "Another study revealed that lipofermata could reduce the uptake of fatty acid by polymorphonuclear myeloid-derived suppressor cells and suppress tumor progression when combined with anti-CTLA4 or anti-PD1 antibodies in lung carcinoma models." (PMID 35910199, 2022). "Programmed cell death protein 1 (PD-1) antibodies as well as PD-L1 antibodies and cytotoxic T-lymphocyte-associated Protein 4 (CTLA-4) inhibitors led to improved PFS and OS in patients with advanced or recurrent lung cancer and are approved for routine use in NSCLC in various combinations." (PMID 34439187, 2021). "Immune checkpoint inhibitors (ICIs) including programmed death-ligand 1 (PD-L1)/programmed death-1 (PD-1) and cytotoxic T-lymphocyte antigen-4 (CTLA-4) have been used for different histologic types of cancer including primary lung cancer that represents the most common and fatal cancer globally." (PMID 34490104, 2021). "The Rab37/IL-6/STAT3/PD-1 axis in immune cell models prompted us to determine whether concurrent blockade of IL-6 and CTLA-4 in vivo would provide a rational treatment to circumvent current PD-1-targeted immune-modulatory therapy for lung cancer." (PMID 34093869, 2021).
lung cancer (continued). "Monoclonal antibodies targeting the CTLA-4 pathway (ipilimumab), PD-1 (nivolumab and pembrolizumab), and PD-L1 (durvalumab, atezolizumab, and avelumab) have achieved promising improvements in second-line therapy for advanced lung cancers." (PMID 34368141, 2021). "However, the reported objective response rate of PD‐1 and CTLA‐4 pathway inhibitors in lung cancer is 10–20%." (PMID 32237066, 2020). "Also, CTLA4, PD-1, and programmed death ligand-1 (PD-L1) inhibitors have shown promising results in lung cancer, yet the response was unclear in advanced-stage GC." (PMID 33292276, 2020). "In the present study, we first reported that mutation in Atrx sensitizes lung cancer to both anti-PD1 and anti-CTLA4, which indicates that Atrx may act as a biomarker of immune therapy and facilitate patient stratification." (PMID 33409155, 2020). "Although CTLA4 expression was found in multiple tumours including non‐small cell lung cancer (NSCLC) tissues and cells, its function in tumour cells is unknown." (PMID 30378264, 2019). "Ipilimumab targets CTLA-4 and is awaiting approval for lung cancer treatment." (PMID 31590386, 2019). "Our results may implicate a direction in the investigation of CTLA-4 in the biology of T effector cells in lung cancer." (PMID 31010080, 2019). "The similar expression pattern of CTLA4 and PD‐L1 in lung cancer cells prompted us to investigate whether one protein affect the expression of the other." (PMID 30378264, 2019). "Lung cancer environment reflected by BALF was enriched with CTLA-4 positive maturated lymphocytes." (PMID 31867335, 2019). "Despite evidence of durable responses, currently approved antibodies against the immune regulators CTLA4 and PD-1/PD-L1 in lung cancer are effective only in subsets of patients, and resistance after an initial response may occur." (PMID 31590386, 2019). "Meanwhile, PD-1 and CTLA-4 were also induced in rM81 EBV(+) lung cancer cells." (PMID 31159203, 2019). "In lung cancer, anti-CTLA-4 and anti-PD-1/PD-L1 blocking antibodies have shown therapeutic success." (PMID 31729963, 2019). "The goal of lung cancer immunotherapy is to improve the cytotoxic effect of lymphocytes by inhibiting suppressory molecules, such as: programmed death-1 (PD-1) and cytotoxic T cell antigen 4 (CTLA-4)." (PMID 31010080, 2019). "In lung cancer PD-1/PD-L1 inhibitors were shown to be superior over chemotherapy, recently a durable effect of combination therapy with anti-PD-1 nivolumab and anti-CTLA-4 ipilimumab in advanced cancer was shown." (PMID 31867335, 2019). "In addition, in the 2 eligible studies for expression position of CTLA-4 protein in lymphocytes, one study is for lung cancer and the other for laryngeal carcinoma." (PMID 28211499, 2017). "The proportion of CD4+/CD25high/Foxp3+/CD127- Tregs determined by flow cytometry and the proportion of Tregs with expression of (in)CTLA-4 were significantly elevated in the BALF harvested from the lung affected by lung cancer when compared with the last two compartments." (PMID 27866241, 2017). "Yet, little is known about the lung population of Tregs with CTLA-4 expression in the lung cancer microenvironment and the difference between (s) and (in) CTLA-4 on Tregs, which may be important for their function." (PMID 27866241, 2017). "Given a higher objective response rate of anti-PD-1 and anti-CTLA-4 in PD-L1 positive lung cancer, it is reasonable to consider adding anti-PD-1 and/or anti-PD-L1 antibodies to the treatment of ALK+ lung cancer, particularly at the time of resistance to ALK inhibitor monotherapy." (PMID 29189709, 2017). "Another early phase I/II trial investigating the same combination in SCLC patients is recruiting (NCT01928394), and multiple other clinical trials are likewise evaluating the combination of anti-CTLA-4 and anti-PD-L1 therapy in lung cancer patients (NCT02261220, NCT02000947, NCT01975831)." (PMID 29546098, 2015).
lung cancer (continued). "The other available studies performed in lung cancer cells focused on CTLA-4 protein expression." (PMID 23936819, 2013). "In addition to traditional surgical treatment and chemotherapy, targeted therapies represented by EGFR inhibitors, ALK inhibitors, ROS1 inhibitors and immunotherapies represented by PD‐1/PD‐L1 inhibitors and CTLA‐4 inhibitors are playing an increasingly critical role in the treatment of lung cancer." (PMID 40845073, 2025). "CTLA-4 expression may vary across different stages of lung cancer, including NSCLC and SCLC." (PMID 39941799, 2025). "Notably, certain genes, such as CTLA4, MZB1, NIP7, and BUB1B in ADC, as well as GNG11 and CCNB2 in SCC, were found to be associated with tumor size, adding a crucial dimension to our understanding of lung cancer biology." (PMID 38612418, 2024). "The previous study indicated that CTLA4 was highly expressed and positively correlated with the clinical stage of non‐small cell lung cancer, and CTLA4 blockade could promote the infiltration of immune cells and derived loss of Treg stability in glycolysis‐low tumor." (PMID 37277111, 2023). "Various research studies indicated that now lung cancer immunotherapeutic therapy aims to enhance the cytotoxological action of lymphocytes by restricting the activities of suppressor molecules such as cytotoxic T cell antigen 4 (CTLA-4) and programmed death-1 (PD-1)." (PMID 36552956, 2022). "The clinically most relevant receptors are the cytotoxic T-lymphocyte-associated protein 4 (CTLA-4) and programmed cell death protein 1 (PD-1) as they can be blocked by targeted therapies which are currently used for various malignant tumor types, including lung cancer." (PMID 35158841, 2022). "Indeed, when used as single or combinatorial agents, antibodies blocking CTLA-4, PD-1, PD-L1, and other checkpoint molecules activate anti-tumor T cells and have had success in the clinic for the treatment of skin and lung cancers among others, significantly extending the lives of patients." (PMID 34204485, 2021). "Summarizing these initial results, our study describes the relevance of PD‐1, CTLA‐4, and NKG2D immunocheckpoints on immune cells subsets and, even greater, their value as biomarkers associated to complete pathological response to neoadjuvant chemoimmunotherapy in lung cancer patients." (PMID 34323406, 2021). "Overexpression of CTLA-4 by lymphocyte subsets might be closely correlated with lung cancer." (PMID 33014010, 2020). "Multiple agents targeting PD1, PD-L1, or CTLA-4 are widely applied as immune checkpoint inhibitors (ICIs) which alleviate the suppression of immune regulatory machineries and lead to immunoablation of once highly refractory cancers such as stage IV lung cancer." (PMID 31703740, 2019). "Pretreatment with epigenetic drugs prior to immune checkpoint modulators such as CTLA-4, PD-1, and PD-L1 inhibitors has shown observable responses in lung cancer patient; cytotoxic chemotherapy after epigenetic therapy has also shown remarkable responses in lung cancer." (PMID 29270240, 2017). "Thus, the combination use of PD-1 and CTLA-4 inhibitors does not increase the risk of flare or de novo irAEs and could be used in lung cancer patients with PAD." (PMID 40469290, 2025). "By using CTLA-4 antibodies, it is possible to block the binding of CTLA-4 to CD80/CD86, weakening the inhibition of T cell activation and enhancing the role of the immune system against lung cancer." (PMID 40861450, 2025). "EVs also increased PD-1, CTLA-4, FOXP3, TNF-α, IL-12, and INF-γ mRNA in lung cancer patients’ immune cells." (PMID 40725070, 2025). "MiR-33a and CTLA-4 expression are negatively correlated in lung cancer, high expression of miR-33a can inhibit CTLA-4 to improve lung cancer survival apparently." (PMID 40296912, 2025). "Targeting of CTLA-4 together with MEK, using trametinib or selumetinib, resulted in increased survival in KRAS-mutant lung cancer mouse models." (PMID 38731852, 2024).